CRP (C-reactive protein)
Diseases named in the same sentence as CRP in open-access papers (continued):
Sharing a sentence is not in itself a finding about the gene and the disease.
multiple myeloma (continued). "Interleukin 6 (IL-6), vascular endothelial growth factor (VEGF), tumor necrosis factor-alpha (TNF-α), C-reactive protein (CRP), and lactate dehydrogenase (LDH) were also involved in the pathogenesis of myeloma." (PMID 35919637, 2022). "The other parameters in disease activity and cytokine involved in the pathogenesis of myeloma were IL-6, VEGF, TNF- α, CRP, and LDH." (PMID 35919637, 2022). "It utilises four widely used and readily available baseline patient and disease parameters: age, WHO performance status (PS), C-reactive protein (CRP), and myeloma International Staging system (ISS)." (PMID 35015781, 2022). "In this study, we analyzed the prognostic significance of PLP2 expression in MM patients using IHC analysis and GEO datasets and correlated with markers of myeloma activity, such as lower serum levels of ALB, higher serum levels of β2-MG, LDH, and CRP." (PMID 32596309, 2020). "Inflammatory parameters such as C-reactive protein (CRP) and interleukin-6 (IL-6) at diagnosis have been also reported as prognostic in patients with multiple myeloma." (PMID 24963470, 2014). "Furthermore, CRP promotes the phosphorylation of p38 MAPK, contributing to elevated ROS levels in multiple myeloma, which further exacerbates cellular stress and apoptosis." (PMID 39932324, 2025). "Some old data seem to be contrasted since a study concluded that CRP did not reflect disease status in multiple myeloma patients, but another study highlighted its independent prognostic significance for the condition." (PMID 37873776, 2023). "CRP promotes myeloma cell survival via a CD32-dependent pathway involving PI3 kinase, ERK, and NF-κB, and CRP can stimulate the proliferation of U266 multiple myeloma cells by up-regulating the expression of survivin and HSP90α proteins." (PMID 29202702, 2017). "CRP has been shown to related to its plasma level in multivariate analysis, is elevated in certain inflammatory conditions including HIV infection and also in haematological conditions including myeloma." (PMID 26629900, 2015). "For myeloma it is well known that interleukin-6 (IL-6) plays a crucial role in the cytokine network, regulating the growth and survival of myeloma cells and stimulating the acute-phase protein synthesis, notably C-reactive protein (CRP)." (PMID 16969356, 2006). "Potential confounding by myeloma-derived inflammation has not been supported by correlations with indices of inflammation (interleukin-6 (Il-6) and C-reactive protein (CRP)), though circulating markers may not reflect local tissue levels." (PMID 32486490, 2020). "Elevated CRP at diagnosis has a negative impact on myeloma prognosis." (PMID 30202676, 2018). "However, the prognostic significance based on preoperative CRP has not been clarified for myeloma patients, yet." (PMID 16969356, 2006). "Similarly, no significant trends in percentage of myeloma infiltration in the bone marrow were noted regarding laboratory results, including LDH, serum M protein, albumin, CRP, and uric acid." (PMID 36769265, 2023).
joint disease (64 papers, 2007 to 2026). "The authors concluded that even if according to standard guidelines, children with joint effusion associated with fever, high CRP level, and WBC count are suspected to have SA and should undergo joint aspiration and antibiotic treatments; this is insufficient to discriminate JIA and SA." (PMID 31779271, 2019). "At least 20% improvement according to ACR criteria (ACR20), 28-joint disease activity score using C-reactive protein [DAS28(CRP)] were used as primary endpoints." (PMID 40666511, 2025). "The most common mild adverse events, in descending order of incidence, were treatment-induced joint pain (n = 7; 87.5%), increased CRP (n = 5; 62.5%), and joint effusion (n = 3; 37.5%)." (PMID 39920220, 2025). "For joint disease activity scores, reductions from baseline in serum CRP and SAA levels at Week 100 of guselkumab treatment positively correlated with improvements in DAPSA and cDAPSA scores." (PMID 39493888, 2024). "Most criteria for diagnosing joint diseases include the measurement of C-reactive protein (CRP) and erythrocyte sedimentation rate (ESR) which are inflammatory markers." (PMID 39435164, 2024). "Outcome indicators included American College of Rheumatology 20% response (ACR20), ACR50, ACR70 and the percentage of patients achieving 28-joint disease activity score using C-reactive protein (DAS28(CRP))<2.6 at 12 weeks and 24 weeks." (PMID 38725657, 2024). "It has already been reported that the levels of circulating CRP correlate with CRP concentrations in the synovial fluid following periprosthetic joint infection, and in several joint diseases such as RA, OA and PA." (PMID 36830710, 2023). "The significantly lower concentration of CS/DS in the urine of children with arthropathy, which correlates negatively with CRP values, probably reflects a “depletion” of the tissue pool of these GAGs." (PMID 38136608, 2023). "The post hoc power of the one-way analysis of variance for the comparison of serum hs-CRP levels between SI joint ankylosis (calculated effect size 0.30, α = 0.05, total sample size 79) was 0.85." (PMID 36615149, 2023). "Baseline CRP, SAA, and IL-6 levels were positively associated with baseline joint disease severity as measured by the DAS28-CRP (p ≤ 0.0001 for each biomarker)." (PMID 37587493, 2023). "Because ESR has a longer half-life than CRP, it is more indicative of a persistent, deep-seated joint disease process." (PMID 35241107, 2022). "Serum calprotectin level has been reported as a more sensitive biomarker of joint disease and polymorphic disease manifestations in PsA than CRP." (PMID 35872782, 2022). "The results indicated that modified Gancao Xiexin decoction was effective for BD compared with control groups for all the primary outcomes, and for the secondary outcomes of eye lesions, genital ulcers, skin lesions, arthropathy, CRP, and ESR." (PMID 34335839, 2021). "The variables investigated included demographic characteristics, the 28-joint disease activity score with C-reactive protein (DAS28-CRP), painDETECT questionnaire (PDQ), pain self-efficacy questionnaire (PSEQ), and pain catastrophizing scale (PCS)." (PMID 32774569, 2020). "The MBDA score correlates with the 28-joint disease activity score using CRP (DAS28-CRP) and other clinical measures of RA disease activity, and change in MBDA score correlates with change in DAS28-CRP." (PMID 32907614, 2020). "In the PsA patients it was found to be affected by duration of the skin and joint disease, the nail bed thickness, CRP concentration and the swollen joints count." (PMID 30842536, 2019). "In a multivariable model adjusting for average CRP level, baseline SHS, and baseline adiponectin level, each log unit higher level of anti-PAD2 was associated with a 9% lower odds of radiographic joint disease progression (adjOR = 0.91; p = 0.016)." (PMID 30515171, 2018). "Sixty-two out of 65 dogs with joint disease were correctly classified using the clinical decision limit for CRP." (PMID 27793205, 2016).
joint disease (continued). "In patients with arthropathies, sCD14 levels in serum correlated positively with CRP levels and sCD14 was therefore characterized as an acute-phase protein, produced mainly by hepatocytes." (PMID 20302606, 2010). "Physicians judged child's functional ability as worse than the parents with greater severity of joint disease, higher CRP, higher frequency of Steinbrocker functional class ≥ II, and greater articular damage, as measured with the JADI." (PMID 18072960, 2007). "Additionally, we explored the impact of RA activity control on poor outcomes based on the 28-joint disease activity score using C-reactive protein (DAS28-CRP)." (PMID 40004909, 2025). "The adverse events observed in three or more patients, in descending order of incidence, were joint pain (n = 7; 87.5%), increased C-reactive protein (CRP) levels (n = 5; 62.5%), treatment-related pain (n = 4; 50.0%), fever, and joint effusion (n = 3; 37.5% each)." (PMID 39920220, 2025). "Furthermore, soluble proteins such as the classical short pentraxin C-reactive protein (CRP), in addition to acting as acute phase reactants and indicator of systemic inflammation, also reflect joint disease activity and tissue pathology." (PMID 34248970, 2021). "Unlike macrophages or monocytes, NLRP3 mRNA levels, ASC and pro-caspase-1 levels were reduced in neutrophils from RA patients, while the level of active caspase-1 was elevated and positively correlated with the CRP-based 28 joint disease activity score (DAS28-CRP)." (PMID 35095918, 2021). "Furthermore, the concentrations of serum and synovial fluid interleukin (IL) 6 concentrations were measured in dogs with joint disease and in healthy dogs, and were correlated to serum CRP concentrations." (PMID 27793205, 2016). "These outcomes were spondylosis, unspecified joint disorders, shoulder lesions, unspecified soft-tissue disorders, gastritis (including duodenitis), oesophagitis, diverticular disease of intestine, diaphragmatic hernia, bronchitis, unspecified headache disorders and C-reactive protein levels." (PMID 37013595, 2023). "Our study indicates that systemic inflammation, as reflected in an elevated CRP, persists in a sizable number of RA patients with minimal or no clinically detectable joint disease and thus may confer increased cardiovascular risk upon these patients." (PMID 19606218, 2009). "RA disease activity was assessed using the 28-joint disease activity score based on ESR (DAS28-ESR), DAS28 based on CRP (DAS28-CRP), simple disease activity index, and clinical disease activity index." (PMID 41560062, 2026). "Next, the prevalence and localization of joint effusion, B- and PD-mode synovitis in MSUS were evaluated against the background of CRP-positivity, gender, type of SSc as well as prevalence of digital ulcerations." (PMID 36743676, 2022). "At baseline, Health Assessment Questionnaire (HAQ) and 28 joint disease activity scores (DAS28) were obtained, and C reactive protein, rheumatoid factor (RF), anticitrullinated protein antibodies (ACPA) and anti-CarP antibodies were measured." (PMID 26443608, 2016). "Clinical parameters of disease activity, including the 28-joint disease activity score (DAS28) and C-reactive protein (CRP), were collected in 34 RA patients and 34 age- and sex-matched healthy controls." (PMID 26435567, 2015). "The correlation of the erythrocyte sedimentation rate, C-reactive protein (CRP) and 28-joint disease activity score (DAS28) with the ultrasound parameters were analyzed." (PMID 25371736, 2014). "Elevated serum inflammatory biomarkers, such as serum C-reactive protein (CRP) and erythrocyte sedimentation rate (ESR) may be the primary indications of chronic PJI due to atypical clinical symptoms such as joint effusion, pain, swelling, and redness." (PMID 34372816, 2021).
joint disease (continued). "ROMs: reactive oxygen metabolites, CRP: C-reactive protein; MMP-3: matrix metalloproteinase-3, DAS28: 28-joint disease activity score, CDAI: clinical disease activity index, ESR: erythrocyte sedimentation rate; SDAI: simplified disease activity index, HAQ: health assessment questionnaire." (PMID 34938634, 2021). "Despite the theoretical advantages, simple measures such as erythrocyte sedimentation rate (ESR) and C-reactive protein (CRP) are not specific to joint disease and the predictive value seems unreliable." (PMID 34887865, 2021). "According to the present data and given that structural damages in RA are believed to be largely irreversible albeit preventable by tight control of joint disease, we suggest that ACPA should be searched in ASS patients, especially those with severe polyarthritis and high CRP amount." (PMID 25997035, 2015). "S-calprotectin did show strong association with PsA, despite the small number of patients, and our findings indicate that S-calprotectin reflects the burden of the joint disease, even in those patients with only a few joints involved and who often have normal ESR and/or CRP." (PMID 24955375, 2014). "Notably, while concentrations of all three mediators were observed to display a negative correlation with joint disease activity (i.e. DAS28 scores), plasma C-reactive protein and erythrocyte sedimentation rate, only correlations between MCTR3 and these parameters were statically significant." (PMID 35430453, 2022). "In comparison to RA, erythrocyte sedimentation rate (ESR) and C-reactive protein (CRP) levels are not as diagnostically reliable when measured in samples from patients with PsA as both, or either, are often within the normal range despite the presence of an advanced joint disease." (PMID 24955375, 2014).
carotid atherosclerosis (63 papers, 2008 to 2025). A thickening and loss of elasticity of the walls of carotid arteries that occur with formation of atherosclerotic plaques. "A study based on the prospective, population‐based Rotterdam Scan confirmed that higher levels of CRP were significantly associated with the presence and progression of WMHs, even after adjusted cardiovascular risk factors and carotid atherosclerosis." (PMID 36478511, 2023). "There was an association between RA patients who harbored carotid atherosclerosis and inflammatory markers such as CRP*, ESR* and IL-6** and VCAM-1*, a marker of endothelial impairment (*p<0.001 and **p<0.05)." (PMID 36249997, 2022). "Previous studies showed that higher hs-CRP levels were associated with higher coronary risk but were less likely to indicate high-risk carotid atherosclerosis." (PMID 28051279, 2016). "Total cholesterol, low density lipoprotein cholesterol, triglycerides and C-reactive protein plasma concentrations were significantly associated with asymptomatic carotid atherosclerosis (p < 0.001)." (PMID 24739810, 2014). "Other studies have concluded that increases in C-reactive protein levels are associated with higher cardiovascular risk only in the presence of carotid atherosclerosis." (PMID 24714990, 2014). "According to our results, increasing age, a high hs-CRP level, and a high E/E’ ratio were closely associated with the presence of subclinical carotid atherosclerosis." (PMID 24192205, 2013). "The purpose of the study was to investigate the association of high sensitiviy c-reactive protein (hsCRP) along with major cardiovascular (CV) risk factors on early carotid atherosclerosis progression in a large, population-based cohort study." (PMID 22208681, 2011). "Several studies demonstrated that C-reactive protein (CRP) and MS are associated with carotid atherosclerosis differently in different sexes indicating different sex hormones might be associated with MS and CRP in different sexes." (PMID 38660513, 2024). "In the REGARDS study, CRP was approved as a prognostic indicator for primary prevention for patients with a high risk of cardiovascular disease, defined as Framingham coronary risk score ≥ 10% or atherosclerotic heart disease (ASCVD) risk ≥ 7.5%." (PMID 35621834, 2022). "In respect to the carotid atherosclerosis, an association between CRP levels and the presence of carotid plagues has been demonstrated by univariate analysis in a prospective studies conducted in general community, or in healthy middle aged women with a smoking history." (PMID 18513415, 2008). "Furthermore, CRP levels were found to be associated with the extent of carotid atherosclerosis." (PMID 18518944, 2008). "These CRP findings align with the conclusions drawn from previous research assessing various markers of carotid atherosclerosis in individuals with T2D." (PMID 41296388, 2025). "It is suggested that CRP is more predictive for cardiovascular prognosis in subjects of established carotid atherosclerosis." (PMID 24616825, 2014). "A multivariate analysis showed that age, hs-CRP, and E/E’ were significant determinants of carotid atherosclerosis." (PMID 24192205, 2013). "The area under the ROC curve of age, hs-CRP and E/E’ ratio to predict carotid atherosclerosis were 0.782 (0.690 - 0.851), 0.745 (0.661 - 0.830), and 0.726 (0.623-0.801), respectively." (PMID 24192205, 2013). "High-normal UCB may be protective against carotid atherosclerosis by its anti-inflammation effect, which was indicated by significantly decreased CRP levels from the lowest to highest UCB quintiles." (PMID 36407305, 2022). "Addition of CRP as a covariate in the model also did not change the results in the female subgroup, showing that FGF21 associated with carotid atherosclerosis independent of CRP concentrations or inflammation." (PMID 33996935, 2021).